UCA1 (urothelial cancer associated 1)
Diseases named in the same sentence as UCA1 in open-access papers (continued):
Sharing a sentence is not in itself a finding about the gene and the disease.
oral squamous cell carcinoma (16 papers, 2017 to 2025). "YAP/TAZ-mediated expression of Neuronal Growth Regulator 1 (NERG1) and Urothelial Cancer Associated 1 Non-coding RNA (UCA1) is required for TGFβ-induced tumorigenic effects in oral squamous cell carcinoma." (PMID 29642615, 2018). "Among numerous lncRNAs, OIP5-AS1, MALAT1, UCA1, CCAT1, and MEG3 have been implicated in oral squamous cell carcinoma, and these lncRNAs were included in this study." (PMID 40568293, 2025). "Previous study suggested that lncRNA UCA1 accelerated proliferation of oral squamous cell carcinoma and enhanced drug resistance to DDP through stimulating DNA damage repair." (PMID 36864456, 2023). "In another study, a connection between long non-coding RNA urothelial cancer-associated 1 (lncRNA UCA1) and repression of miR-184 has been found; thus, this promotes proliferation and cisplatin resistance of oral squamous cell carcinoma." (PMID 34946938, 2021). "Finally, in oral squamous cell carcinoma (orSCC), UCA1 acted as a competitive endogenous RNA (ceRNA), sponging miR-184." (PMID 41379397, 2025). "Silencing of UCA1 suppressed proliferation and metastasis and induced apoptosis of oral squamous cell carcinoma cell lines, which may be related to the activation of the WNT/β-catenin signaling pathway." (PMID 31694571, 2019). "Silence UCA1 suppressed cell proliferation and metastasis and induced cell apoptosis of oral squamous cell carcinoma, which might be significantly correlated with the activation level of the Wnt/β-Catenin signaling pathway." (PMID 30918102, 2019). "However, the function and molecular mechanism of UCA1 implicated in cisplatin (CDDP) chemoresistance of oral squamous cell carcinoma (OSCC) is still not fully established." (PMID 29125238, 2017).
bladder transitional cell carcinoma (15 papers, 2014 to 2023). The most common morphologic subtype of urinary bladder carcinoma (over 90% of cases). "UCA1, which is also known as urothelial carcinoma associated 1, is a lncRNA that was originally identified in bladder transitional cell carcinoma." (PMID 29137343, 2017). "Urothelial carcinoma-associated 1 (UCA1) is a new lncRNA-encoding gene belonging to human endogenous Retrovirus-H family and was originally identified in bladder transitional cell carcinoma." (PMID 28248879, 2017). "Urothelial Cancer Associated 1 (UCA1) is a lncRNA originally identified in bladder transitional cell carcinoma." (PMID 27148353, 2016). "Linc00178 is located on 19p13.12 and was first identified in bladder transitional cell carcinoma; thus, linc00178 is also known as urothelial cancer associated 1 (UCA1)." (PMID 36831352, 2023). "Urothelial Cancer associated 1 (UCA1) is a 1,400 nucleotide long lincRNA that was first identified as a marker of bladder transitional cell carcinoma." (PMID 35154157, 2022). "UCA1 (Urothelial carcinomaassociated 1) serves as an oncogenic lncRNA and is originally recognized in bladder transitional cell carcinoma." (PMID 32760219, 2020). "UCA1 expression in many kinds of tumor tissues is higher than that in the corresponding control tissues, such as bladder urothelial carcinoma (BLCA), cholangiocarcinoma (CHOL), lung squamous cell carcinoma (LUSC), stomach adenocarcinoma (STAD), and thyroid carcinoma (THCA)." (PMID 34238213, 2021). "UCA1 is originally identified in bladder transitional cell carcinoma." (PMID 27992369, 2017). "UCA1.UCA1 is highly expressed in bladder transitional cell carcinoma." (PMID 25543668, 2014).
tongue squamous cell carcinoma (14 papers, 2014 to 2022). A squamous cell carcinoma that arises from the tongue. "Urothelial cancer-associated 1 (UCA1) lncRNA has been revealed significantly elevated in tongue squamous cell carcinoma tissues (P < .0001) and was statistically correlated with lymph node metastasis (P = .0371)." (PMID 28403886, 2017). "Moreover, silencing of lncRNA urothelial cancer-associated 1 is reported to enhance the cisplatin chemosensitivity in tongue squamous cell carcinoma cells." (PMID 31528122, 2019). "For example, knocking down the expression of the lncRNA UCA1 can significantly enhance tongue squamous cell carcinoma apoptosis in response to CDDP treatment through a mechanism linked to the inhibition of CDDP-induced PI3K/Akt signaling." (PMID 34790046, 2021). "Moreover, lncRNA UCA1 is upregulated in tongue squamous cell carcinoma (TSCC) and promotes proliferation, migration, invasion and glycolysis metabolism of TSCC cells." (PMID 33652661, 2021). "Additionally, UCA1 might function as an oncogene in tongue squamous cell carcinoma (TSCC) through regulating the miR‐138‐5p/ CC chemokine receptor (CCR7) axis, and the interaction between miR‐138‐5p and UCA1 or CCR7 has been identified." (PMID 33565716, 2021). "Also, overexpression of UCA1 lncRNA could promote metastatic but not proliferation ability of tongue squamous cell carcinoma cells." (PMID 26136615, 2015).
lung adenocarcinoma (11 papers, 2020 to 2025). A carcinoma that arises from the lung and is characterized by the presence of malignant glandular epithelial cells. "This study aimed to explore the mechanism of LncRNA urothelial carcinoma-associated 1 (UCA1) promoting cisplatin resistance in lung adenocarcinoma (LUAD)." (PMID 34544452, 2021). "Research on the role of lncRNA UCA1 in cisplatin resistance in lung adenocarcinoma outlines several mechanisms through which UCA1 influences the expression of various genes, including ChaC1." (PMID 39534397, 2024). "The downregulation of ChaC1, along with other genes, appears to contribute to the mechanisms by which lung adenocarcinoma cells develop resistance to cisplatin, highlighting the UCA1-TXNIP axis as a potential therapeutic target for overcoming drug resistance." (PMID 39534397, 2024). "Specifically, UCA1 is found to be highly expressed in cisplatin-resistant lung adenocarcinoma cells, and its expression correlates with the downregulation of several mRNAs, including ChaC1." (PMID 39534397, 2024). "Increasing evidence suggest that UCA1 functions as an oncogene, which plays an important role in the tumorigenesis and development of different types of cancer, including papillary thyroid carcinoma, pancreatic cancer (PC) and lung adenocarcinoma." (PMID 33777227, 2021). "Compared to cisplatin-sensitive cells, cisplatin-resistant cells exhibit downregulation of TXNIP mRNA mediated by UCA1, suggesting a role of UCA1 and TXNIP in contributing to cisplatin resistance in lung adenocarcinoma." (PMID 37794178, 2023). "To confirm the roles of lncRNA UCA1, miR-1-3p and DLD in LUAD, we further verified their differential expressions in normal lung epithelial cells (BEAS-2B) and different lung adenocarcinoma cell lines (A549 and H1299) by in vitro cell experiments." (PMID 36110528, 2022).
bladder tumor (10 papers, 2017 to 2024). "The lncRNA urothelial carcinoma-associated 1 (UCA1) is involved in bladder tumor progression and identified as an oncogenic HIF1A target gene." (PMID 35659268, 2022). "Studies have confirmed the association between up regulation of lncRNA urothelial carcinoma associated 1 (UCA1) in bladder tumor tissue with cell growth, invasion, and migration." (PMID 33183321, 2020). "LncRNA-urothelial cancer-associated 1 (lncRNA-UCA1), prevalent in hypoxic tumor-derived exosomes, has been implicated in promoting bladder tumor growth and development." (PMID 38249783, 2024). "Compared with normoxic exosomes, secreted hypoxic 5637 (bladder carcinoma) cell-derived exosomes were found to have higher UCA1 levels and to promote bladder tumor proliferation, migration, and invasion." (PMID 35659268, 2022). "The ectopic expression of UCA1 influences bladder tumor progression, revealing UCA1 as an oncogenic player in bladder carcinogenesis." (PMID 36685879, 2022). "Under hypoxia, UCA1 inhibits apoptosis in bladder tumors cells and promotes their viability by modulating the BCL2-associated X, apoptosis regulator (BAX)/BCL2 apoptosis regulator (BCL2) ratio." (PMID 35659268, 2022). "UCA1 is frequently up regulated in bladder malignancies and contributed to aggressiveness of bladder tumor cells." (PMID 33183321, 2020). "A significant UCA1 up regulation has been shown in bladder tumor tissues following cisplatin treatment." (PMID 33183321, 2020). "Hypoxia also induces production of exosomes containing UCA1 in bladder tumors." (PMID 35659268, 2022). "Therefore, UCA1-dependent CREB activation was considered as a key step in miR-196a-5p transcriptional regulation in bladder tumor cells." (PMID 33183321, 2020). "However, among the sixteen biomarkers, seven of them, namely LINC00355, UCA1-203, HOX-AS-2, Linc-ROR, OCT4, SOX2 and OTX2-AS1, did not demonstrate sufficient discriminatory power to separate bladder tumors from urocystitis, as indicated by their low AUC values (AUC<0.70)." (PMID 31949480, 2020).
myocardial infarction (10 papers, 2016 to 2024). Gross necrosis of the myocardium, as a result of interruption of the blood supply to the area, as in coronary thrombosis. "Circulating lncRNA urothelial carcinoma-associated 1 (UCA1) may serve as a biomarker for acute myocardial infarction." (PMID 37759491, 2023). "UCA1 is also found elevated in serum derived exosomes from patients surviving myocardial infarction, suggesting additional clues towards its protective role." (PMID 33513776, 2021). "MSC derived exosomes containing UCA1 have been shown to sponge miR-873 and prevent apoptosis to ultimately aid in cardio-protection in myocardial infarction model of rat." (PMID 33513776, 2021). "UCA1 was proposed as a novel biomarker for acute myocardial infarction since its plasma levels are significantly decreased 12 h after myocardial infarction but elevated after 72 h in comparison with healthy controls." (PMID 29751665, 2018). "Moreover, the dysregulation of UCA1 was also found in acute myocardial infarction, kidney damage and neurodegenerative diseases." (PMID 28423704, 2017). "Interestingly, the UCA1 was decreased early but upregulated afterwards in the plasma of patients after myocardial infarction." (PMID 26949706, 2016). "Hypoxia preconditioning of human MSCs promoted the generation of exosomes containing lncRNA UCA1 that helped in improving cardiomyocyte survival and cardiac function in a rat model of myocardial infarction (MI)." (PMID 37759491, 2023).
Sepsis (10 papers, 2019 to 2025). Sepsis is defined as life-threatening organ dysfunction caused by a dysregulated host response to infection. "Nevertheless, since UCA1 has been implicated in several inflammatory diseases such as acute respiratory distress syndrome, sepsis, pneumonia, and acute ischemic stroke, we can surmise that UCA1 plays a pro-inflammatory role in psoriasis." (PMID 37076497, 2023). "The content of UCA1 is elevated and related to the disease severity and prognosis in patients with sepsis, which may become the cause of ALI." (PMID 37321562, 2023). "Reducing HOXA1 expression by UCA1 overexpression aggravates the progression of sepsis‐induced pneumonia." (PMID 39713961, 2025). "Our results were further validated in an in vivo model of sub-lethal LPS-induced sepsis, whereby siRNA mediated knockdown of UCA1 and HULC lncRNAs prevented induction of VCAM1, ICAM1, and IL6, as assayed by immunohistochemistry." (PMID 31231228, 2019). "Cumulatively, these results suggest that LPS induced in vitro sepsis in endothelial cells and induction of pre-inflammatory mediators are at least in part due to increased expression of the UCA1 and HULC lncRNAs." (PMID 31231228, 2019). "The results from the current study show that along with lnc-IL17R, lncRNAs MALAT-1, HULC, and UCA1 are also upregulated during LPS induced sepsis." (PMID 31231228, 2019). "This implied that the specific mechanism of UCA1 in sepsis still needs validation." (PMID 38750059, 2024). "This regulation was similar to the role of UCA1 in sepsis and neurological injury." (PMID 36160709, 2022). "Given our in vivo results it seems that targeted knockdown of HULC and UCA1 might be a viable therapeutic option for sepsis, even though long-term stability and directed organ-specific delivery will be potential problems." (PMID 31231228, 2019). "Increasing evidences demonstrate that lncRNAs are essential regulators of inflammatory response and potential biomarkers of sepsis, including NEAT1, HOTAIR, UCA1 and HULC." (PMID 36817490, 2023). "At present, studies of lncRNA expression in sepsis mainly focus on HOTAIR, MALAT1, NEAT1, TUG1, and UCA1." (PMID 34514170, 2021). "Taken together, these results indicate that increase in proinflammatory ICAM1, VCAM1, and IL6 in HMECs during LPS induced sepsis in vitro is at least in part due to increase in expression of the lncRNAs HULC and UCA1." (PMID 31231228, 2019). "It is highly possible that there are other targets whose expression is also modulated following induction in expression of the HULC, UCA1, and MALAT-1 lncRNAs during sepsis in endothelial cells." (PMID 31231228, 2019). "RIP and qRT-PCR analysis revealed that the lncRNAs HULC, UCA1, and MALAT-1 were significantly enriched with the CMPs after sepsis." (PMID 31231228, 2019).
epilepsy (9 papers, 2019 to 2025). A brain disorder characterized by episodes of abnormally increased neuronal discharge resulting in transient episodes of sensory or motor neurological dysfunction, or psychic dysfunction. "In addition, UCA1 reportedly reduced epilepsy and seizure-caused brain injury by modulating miR-495 expression." (PMID 32404536, 2020). "These insights position UCA1 as a promising therapeutic target and underscore the potential of lncRNA-based strategies for epilepsy intervention." (PMID 40791576, 2025). "Wang and collaborators suggested that lncRNA-UCA1 is capable of inducing or worsening epilepsy in a pilocarpine-induced rat model by interacting with NF-kB and that UCA1 expression in peripheral blood correlated positively with that of brain tissue." (PMID 35328484, 2022). "For instance, lncRNA UCA1 expression was revealed to be decreased in epilepsy and seizure-induced brain injury, which was in line with our results." (PMID 33686956, 2021). "And UCA1 up-regulation reduces the frequency of epilepsy seizures and promotes learning and memory in temporal lobe epilepsy rats." (PMID 34675776, 2021). "The authors concluded that the expressions of NF-Kb and UCA1 are in the dynamic change in the formation of epilepsy, which suggests a role of UCA1 in the pathogenesis of the disease." (PMID 31581735, 2019). "In particular, Geng and colleagues found that Nrf2 was negatively regulated by miR-495 and that lncRNA UCA1 was down-regulated and miR-495 was up-regulated in pilocarpine-induced epilepsy rat models." (PMID 31581735, 2019). "Concerning its potential involvement in epilepsy, UCA1 resulted abnormally methylated in the hippocampus of TLE patients after surgical resection, although the SE underlying mechanism was not studied." (PMID 31581735, 2019). "LncRNA UCA1 could suppress pilocarpine-induced epilepsy by inhibiting apoptosis of hippocampal neurons via miR-495/Nrf2-ARE pathway." (PMID 36278003, 2022). "Results of pre-clinical studies showed that the expressions of LncRNA H19 and LncRNA X inactive specific transcript (XIST) were up-regulated, while the expressions of LncRNA PVT1, LncRNA CACS2, and LncRNA UCA1 were down-regulated in epilepsy animal or cell models." (PMID 36278003, 2022). "In addition, UCA1 regulates the inflammatory responses in epilepsy by regulating the miR-203-mediated myocyte enhancer factor 2C/NF-κB signaling pathway." (PMID 33777227, 2021). "Moreover, LncRNA UCA1 could inhibit the inflammation via regulating miR-203 mediated regulation of MEF2C/NF-κB signaling in epilepsy." (PMID 36278003, 2022). "LncRNA UCA1 was downregulated in epilepsy, whereas the UCA1/miR-203/MEF2C axis inhibited the activation of NF-κB signaling pathway and IL-6, TNF-α, and Cox-2 levels in epilepsy." (PMID 33776905, 2021). "The down-regulated LncRNA PVT1, LncRNA CACS2, and LncRNA UCA1 could, respectively, regulate the downstream proteins including BDNF, PTEN, or JAK to promote the activation of astrocytes and the progression of epilepsy." (PMID 36278003, 2022). "UCA1 over-expression abrogates astrocyte activation and suppresses the expression of astrocyte glutamate aspartate transporter (GLAST) (one factor related to epilepsy) in vivo." (PMID 34675776, 2021). "In non-cancerous diseases, UCA1 can limit the inflammatory responses in epilepsy, and UCA1 expression is higher in patients with non-refractory epilepsy than those with refractory epilepsy." (PMID 33777227, 2021).